CAT (catalase)
Diseases named in the same sentence as CAT in open-access papers (continued):
Sharing a sentence is not in itself a finding about the gene and the disease.
Hepatitis (11 papers, 2010 to 2022). Inflammation of the liver. "A decrease in CAT activity was suggested by a reduction of the electron density of the peroxisomal matrix, frequently observed in hepatitis, and by a heterogeneous distribution of the CAT reaction product leaving a small transparent zone." (PMID 34571897, 2021). "Then, we decided to assess catalase activity, since this enzyme is one of the most important antioxidants in the context of hepatic IR." (PMID 26798418, 2016). "Also, rats administrated BP had a significant lower MDA and higher GSH, GPx, and CAT than the hepatitis group." (PMID 34344946, 2021). "Animals treated with fluvastatin (hepatitis group) had a significantly higher MDA level and a significantly lower GSH level and antioxidant activities of GPx and CAT in their livers than control animals." (PMID 34344946, 2021). "Antioxidant enzymes; CAT, POD and SOD or a molecule such as glutathione in liver tissue play important role against reactive oxygen species and show curative activity against liver inflammation." (PMID 32917140, 2020). "We found that melatonin treatment slightly increased activities and/or level of antioxidant parameters, among them SOD, catalase and glutathione significantly reduced oxidative lesions named TBARS and lipids hydroperoxides when compared with the CCl4-treated animals with hepatitis injury." (PMID 31238587, 2019). "Surprisingly, rather than a decrease in SODt and catalase activity after CCl4 injection – commonly reported during hepatitis – we observed an increased expression of those antioxidant enzymes whereas NVH treatment tended to lead to their improvement." (PMID 29357846, 2018).
periodontal disease (11 papers, 2007 to 2024). "The objective of this study was to explore associations of genetic polymorphisms and salivary expressions of MnSOD and catalase with the effectiveness of periodontal disease treatment." (PMID 31470840, 2019). "Studies examining the association of antioxidant enzymes CAT and GPX with periodontal disease are scarce, and to our knowledge, this is the first study examining these parameters in children and young teenagers with gingivitis." (PMID 34204920, 2021). "There was also a tendency towards promoter region methylation on the CAT sequence of individuals with periodontal disease." (PMID 32267380, 2020). "Since then, the implication of ROS and their degrading enzymes SOD or CAT in the pathogenesis of periodontal diseases has been supported by several groups." (PMID 25374447, 2014). "Ellis and collaborators analyzed gingival tissues from patients withsevere periodontal disease and showed that the activity of catalase wasdecreased." (PMID 18288271, 2007). "This could explain the decrease in the catalase for patients with periodontal diseases at an advanced stage." (PMID 31640685, 2019). "Analysis of the level of SOD, CAT, and GPx in the saliva indicates a decrease in the activity of the enzymatic component of the local antioxidant potential, which allows these parameters to be used as predictors of the escalation of the inflammatory process in periodontal disease." (PMID 33803774, 2021). "Salivary antioxidant activities, such as the total oxidant status, catalase, and SOD, have been useful biomarkers for evaluating the severity of periodontal disease and treatment effectiveness." (PMID 31470840, 2019). "The reduction of plasma antioxidant activities (Catalase, TAOC, GR) may have a role in the pathogenesis of periodontal diseases." (PMID 31640685, 2019).
pulmonary hypertension (11 papers, 2012 to 2025). Increased pressure within the pulmonary circulation due to lung or heart disorder. "At the same time, high expression of CAT is an essential factor in the prognosis of patients with pulmonary hypertension." (PMID 35237384, 2022). "Induction of pulmonary hypertension in Sprague-Dawley rats resulted in increased GPx and decreased CAT activity in animal tissues." (PMID 28638832, 2017). "Similarly, in the development of pulmonary hypertension mitochondrial ROS activate NOXs and to collectively induce a pro-oxidative redox state, which is further favored by the impairment of antioxidant capacity (SOD, catalase and glutathione peroxidase) of pulmonary hypertensive cells." (PMID 31935965, 2020). "The study revealed that crocin affected the oxidation resistance 1 (OXR1) signal pathway in rats by regulating SOD, GSH and CAT, and had a protective effect on MCT-induced pulmonary hypertension." (PMID 39759448, 2024). "In this study, CAT and SOD activities were higher in 400 mg/kg/day MSM-treated pulmonary hypertensive rats than in either the normotensive controls or the MCT-induced pulmonary hypertensive rats." (PMID 23118745, 2012). "MCT-treated rats showed a significant reduction of SOD, CAT, and GPX concentrations and increased MDA levels, which were reversed by 18β-Glycyrrhetinic Acid, and experimental data support the notion that 18β-Glycyrrhetinic Acid is beneficial in the treatment of pulmonary arterial hypertension." (PMID 39759448, 2024). "SO2 could upregulate the activities of antioxidative enzymes, including superoxide dismutase (SOD), glutathione peroxidase (GSH-Px), and catalase (CAT) in lung tissues and plasma from MCT-induced pulmonary hypertensive rats, whereas HDX decreased the activities of antioxidative enzymes." (PMID 26839635, 2016).
rheumatoid arthritis (11 papers, 2014 to 2025). A chronic, systemic autoimmune disorder characterized by inflammation in the synovial membranes and articular surfaces. "SeNP loaded with CAT and functionalized with FA and HA are shown to target activated macrophages associated with rheumatoid arthritis and atherosclerosis via CD44 and FR-βreceptors which are more expressed in these cells." (PMID 34639150, 2021). "Catalase and superoxide dismutase have been found to be associated with oxidative stress in patients with rheumatoid arthritis and systemic lupus erythematosus." (PMID 25995969, 2014). "Activities of some erythrocyte antioxidant enzymes, such as SOD, GPX, and catalase in osteoarthritis (OA) and rheumatoid arthritis (RA), are reduced with respect to physiological conditions." (PMID 36005136, 2022). "Although catalase is significantly increased in rheumatoid arthritis its concentration is very low to expect considerable protection against H2O2." (PMID 25610704, 2014). "Endogenous antioxidant enzymes, including CAT, POD and SOD protect the oxidation induced cartilage destruction in inflammatory conditions such as rheumatoid arthritis." (PMID 30005651, 2018).
acne (10 papers, 2016 to 2025). An inflammatory process of the sebaceous glands which is characterized by comedones, nodules, papules and/or pustules on the skin. "SOD and catalase are specific enzymatic antioxidants that reduce ROS in human skin, and the development of skin diseases such as contact dermatitis, acne vulgaris, and cancer, is associated with an abnormal reduction of these proteins." (PMID 38994364, 2024). "The catalase and superoxide dismutase levels with increased oxidative stress, playing an important role in the pathogenesis of acne." (PMID 33902622, 2021). "In contrast, diminished levels of antioxidant enzymes (e.g. superoxide dismutase and catalase) have been observed in acne." (PMID 34466486, 2019). "Superoxide dismutase (SOD), catalase (CAT), and glutathione (GSH) were also reduced in the skin of people with acne." (PMID 38541239, 2024). "The most commonly used markers to assess OS in acne were MDA, a marker of lipid peroxidation, and the antioxidant enzymes CAT and SOD, which were measured in blood samples (serum/plasma/erythrocytes)." (PMID 37511808, 2023). "When the overall oxidant-antioxidant balance was studied in patients with acne, similar result was reported; the plasma levels of SOD, CAT, Vitamin E and zinc were decreased and plasma MDA level was increased significantly." (PMID 36875194, 2023). "MDA and SOD levels were significantly escalated in acne patients,G6PD and CAT levels were significantly lower in acne patients." (PMID 34466486, 2019). "SOD, CAT and GSH were also found to decrease in the skin of acne patients." (PMID 36875194, 2023). "SOD, CAT, and GSH negatively, and MDA positively correlate with the severity of acne vulgaris." (PMID 34466486, 2019). "Moreover, lower CAT activity and higher SOD activity and MDA levels were observed in plasma of patients with acne vulgaris and lower GSH levels and greater MDA levels in plasma of cutaneous melanoma patients compared with control subjects." (PMID 27057281, 2016).
diabetic retinopathy (10 papers, 2018 to 2025). "Furthermore, diabetic retinopathy‐provoked oxidative stress, including over‐production of reactive oxygen species and malondialdehyde, and attenuated activities of superoxide dismutase and catalase were all restored by GSP." (PMID 41409191, 2025). "In an in vivo and in vitro study on diabetic retinopathy, a decrease in TIMP3 expression was accompanied by an increase in oxidative stress injury, which was manifested by an increase in ROS and a decrease in SOD and CAT enzyme activities." (PMID 40893347, 2025). "Catalase (CAT) and other novel antioxidants, such as glucagon-like peptide-1 (GLP-1) and exendin-4 (EXE-4; a natural GLP-1 analog) are used as cytoprotective agents for the prevention and treatment of diabetic retinopathy." (PMID 34440748, 2021). "Here, we demonstrated that the administration of CaD, an angiopreventive drug clinically approved for the treatment of diabetic retinopathy, inhibited oxidative stress as revealed by decreased MDA levels and the increased activity of the antioxidative enzymes SOD, GPx, and CAT in brain homogenates." (PMID 33922431, 2021).
endometritis (10 papers, 2022 to 2025). An acute or chronic, usually bacterial infectious process affecting the endometrium. "This study investigates postpartum bovine uterine tissues, comparing inflammatory cytokines (IL-1β, IL-6, TNF-α) and oxidative-stress-related factors (GPx, SOD, CAT) between healthy and endometritis groups." (PMID 40646747, 2025). "With respect to changes in antioxidant/oxidative stress biomarkers, CAT, GPx, NO, SOD and TAC showed a significant decrease associated with a significant increase of MDA in buffalo–cows with endometritis compared to healthy group." (PMID 38459095, 2024). "The comparison of the groups for OS demonstrated that endometritis caused an increase in serum malondialdehyde (sMDA), Cp, and NPT levels (P<0.05), but decreased serum levels of superoxide dismutase (SOD), catalase (CAT), and glutathione (GSH) (P<0.05)." (PMID 36156882, 2022). "We tested for SOD, GPx, and CAT to investigate the antioxidant levels in uterine tissue with endometritis." (PMID 36139304, 2022). "Our results are almost in line with those of50who discovered that in Egyptian buffalo cows with clinical endometritis, the mRNA levels of CAT and GPX had a positive correlation with the blood level of TNF-α (r = 1, P = 0.008 and r = 0.999, P = 0.034), respectively." (PMID 40542007, 2025). "Moreover, in comparison to the healthy uterus, the expression of peroxidase glutathione peroxidase (GPX) (p < 0.01) and catalase (CAT) (p < 0.01) in the uterus with endometritis was markedly reduced, and the expression of superoxide dismutase (SOD) was also lower (p < 0.001)." (PMID 38473153, 2024). "Buffaloes with endometritis showed significantly decreased levels of expression of the NDUFS5, RXFP1, TGF-β, CAT, SOD3, and GPX transcription factors." (PMID 40266925, 2025). "The serum levels of Hp, SAA, Cp, IL-6, IL-10, TNF-α, NO and MDA were significantly (P˂0.05) increased, along with reduction of CAT, GPx, SOD and TAC in buffalo–cows with endometritis compared to healthy ones." (PMID 38459095, 2024). "The RXFP1, NDUFS5, TGF-β, SOD3, CAT, and GPX genes were expressed at substantially lower levels in endometritis-affected buffaloes." (PMID 38459095, 2024). "In the current investigation, buffalo's cows with endometritis showed disrupted oxidative state, with significantly higher MDA and NO levels and lower activity of CAT, GPx, SOD, and TAC values than in healthy animals." (PMID 38459095, 2024). "For the buffaloes with endometritis, TLR4 had the highest possible quantity of mRNA (2.62 ± 0.16) while CAT had the lowest amount (0.52 ± 0.13 mRNA) for each gene." (PMID 39195794, 2024). "In the buffaloes affected by endometritis, the expression levels of the RXFP1, NDUFS5, TGF-β, SOD3, CAT, and GPX genes were significantly reduced." (PMID 39195794, 2024). "In contrary, the mean values of CAT, GSH, and SOD were lower in the endometritis group (P<0.05) compared with the healthy control." (PMID 36156882, 2022). "Furthermore, the RT-qPCR evaluation of the antioxidant-stress-related enzymes (CAT, GPx1, SOD) at the mRNA level indicated that the endometritis group also displayed a marked increase in the mRNA expressions of CAT, GPx1, and SOD compared to the healthy group." (PMID 40646747, 2025). "The levels of the PRLR, LTF, CLA-DRB3.2, beta defensin, TLR2, TLR4, and CCL5 genes were significantly up-regulated in postparturient goats with endometritis compared to tolerant ones, while the GPX4, GST, SOD3, CAT, and ATOX1 gene patterns demonstrated the opposite tendency." (PMID 39195794, 2024). "The following genes were assessed for their expression levels using real-time PCR in both the normal and endometritis-affected buffaloes: immune (TLR4, IL-8, IL-17, NFKB, SLCA11A1, and NCF4) and antioxidant (SOD, CAT, NDUFS6, Nrf2, Keap1, PRDX2, HMOX1, OXSR1, ST1P1, and SERP1)." (PMID 39195794, 2024).
endometritis (continued). "Moreover, the rats with endometritis revealed an increase in MDA concentration and a decrease in the activity of CAT and GSH as compared to healthy control." (PMID 36156882, 2022). "The optimal cut-off value of NPT, Cp, and CAT when using ROC analysis to distinguish between she-camel with and without endometritis were 2.55 ng/mL, 0.11 g/L, and 14.40 (U/mgHb), respectively." (PMID 36156882, 2022).
liver cirrhosis (10 papers, 2014 to 2025). "In the present investigation, there was significant decline in the level of catalase in alcohol control and liver cirrhosis rats." (PMID 40271532, 2025). "The liver cirrhosis resulted in oxidative stress in the ileum tissues, reducing CAT, GSH-Px, and SOD and promoting MDA concentrations compared with the control group." (PMID 37273916, 2023). "The antioxidant potential of ZnSO4 supplementation was observed through the improvement of antioxidant enzymes activity, such as catalase and malondialdehyde levels, as already reported in the rat model of liver cirrhosis." (PMID 32190227, 2020). "In patients with liver cirrhosis, increased prooxidant markers (serum MDA) and decreased antioxidant capacity (red blood cell catalase, SOD, reduced blood GSH) were measured." (PMID 39272729, 2024).
male infertility (10 papers, 2015 to 2026). The inability of the male to effect fertilization of an ovum after a specified period of unprotected intercourse. "Indeed, while low total CAT activity has been associated with male infertility in humans, the total activity of this antioxidant enzyme has been negatively correlated with the fertility of Arabian horses." (PMID 31717586, 2019). "In this study, LDH, CAT, GSH, MDA, and SOD activities were measured to assess oxidative stress, which plays a significant role in male infertility caused by the toxic effects of DOX." (PMID 40451973, 2025). "An association between male infertility, the level of TAC, and the activity of antioxidant enzymes and molecules (catalase, superoxide dismutase, glutathione) was confirmed." (PMID 36290709, 2022). "More specifically, and due to its proven relationship with fertility and normal sperm genesis, the study of catalase activity in seminal samples constitutes a promising field for progress when studying male infertility." (PMID 31963256, 2020). "This review consequently summarises the main current knowledge about the role of the catalase (CAT) enzyme when it comes to male infertility." (PMID 31963256, 2020). "To date, functional polymorphisms of antioxidant genes NRF2, SOD, GST, NOS, CAT, and GPX have been reported to be associated with male infertility in humans." (PMID 26618172, 2015). "In the past two decades, numerous studies have demonstrated that functional polymorphisms or the genetic disruption of the CAT, GPX, GST, NOS, NRF2, and SOD genes was associated with male infertility." (PMID 26618172, 2015). "It follows from this analysis that CAT could play an important role in male fertility and could become a good target for male infertility diagnosis and monitoring." (PMID 31963256, 2020). "Some studies have correlated H2O2 with male infertility and catalase with fertility restoration." (PMID 31963256, 2020). "The findings of these studies indicate that functional polymorphisms in the NRF2, SOD, GST, NOS, CAT, and GPX genes may potentially contribute to genetic causes of male infertility." (PMID 26618172, 2015). "Hence, it can be concluded that lower seminal plasma levels of SIRT1, SIRT3, TAC, SOD and catalase may result in increases in oxidative stress, which impacts on various sperm parameters, thereby leading to male infertility." (PMID 38255792, 2024). "Most of these genes, including NRF2, SOD, CAT, glutathione S-transferase (GST), glutathione peroxidase (GPX), and nitric oxide synthase (NOS), harbor sequence variants in humans, which in turn may cause male infertility in different ways." (PMID 26618172, 2015). "Catalase (CAT) stands out as one of the most efficient natural enzymes when catalysing the split of H2O2 into H2O and O2; H2O2 is one of the reactive oxygen species (ROS) involved in oxidative stress, a process closely related to aging and several health disorders or diseases like male infertility." (PMID 31963256, 2020).
multiple sclerosis (10 papers, 2022 to 2024). A progressive autoimmune disorder affecting the central nervous system resulting in demyelination. "Similar to our findings, TNF treatment of microglial cells in vitro and the excess of TNF in the brains of multiple sclerosis patients or the respective mouse models reduced catalase levels, resulting in oxidative stress." (PMID 38339126, 2024). "The peroxisome proliferator phenylbutyrate reversed the inflammation-induced decrease in ABCD3/PMP70, PEX11β and catalase protein levels and is recommended as a possible drug for treatment of multiple sclerosis." (PMID 37170361, 2023). "Interesting results were obtained from the study of IgG catalase activity in patients with various types of multiple sclerosis." (PMID 35409256, 2022). "In agreement with the results of the current study, an increase in CAT activity and a decrease in SOD activity were observed in patients with multiple sclerosis, which is an age-related disease." (PMID 35463818, 2022). "Previously, we have shown that the serum antibodies of patients with multiple sclerosis have SOD and catalase activity." (PMID 36143234, 2022). "By the end of the experimental protocol, interesting and significant trends among levels of anti-oxidant markers (SOD, CAT, GSH, GPx) activities in multiple sclerosis and the treatment groups were observed." (PMID 35268709, 2022).